PZP (PZP alpha-2-macroglobulin like)
Description:
Is able to inhibit all four classes of proteinases by a unique 'trapping' mechanism. This protein has a peptide stretch, called the 'bait region' which contains specific cleavage sites for different proteinases. When a proteinase cleaves the bait region, a conformational change is induced in the protein which traps the proteinase. The entrapped enzyme remains active against low molecular weight substrates (activity against high molecular weight substrates is greatly reduced). Following cleavage in the bait region a thioester bond is hydrolyzed and mediates the covalent binding of the protein to the proteinase.
Synonyms: CPAMD6
Tractability: Antibody: UniProt places it where antibodies can reach, with medium confidence; UniProt predicts a signal peptide or a membrane-spanning region; its Gene Ontology location is reachable by antibodies, with medium confidence. PROTAC: its protein half-life has been measured.
Gene: Protein-coding gene on chromosome 12 (9,148,840 to 9,208,399, reverse strand). Ensembl gene ENSG00000126838.
Subcellular location: Secreted
Gene Ontology:
Molecular function: endopeptidase inhibitor activity; protease binding
Biological process: female pregnancy
Cellular component: blood microparticle; extracellular exosome; extracellular matrix; extracellular region
Genetic constraint (gnomAD): Loss-of-function variants: 120 observed, 150.03 expected, observed/expected ratio (o/e) 0.8, 90% interval 0.69 to 0.93. The upper end of that interval is the gene's LOEUF score, 0.93, which puts it in group 3 of 6, group 1 being the genes least tolerant of losing a copy. Missense variants: 1,508 observed, 1,648.4 expected, observed/expected ratio (o/e) 0.91, 90% interval 0.88 to 0.95. Synonymous variants: 564 observed, 615.47 expected, observed/expected ratio (o/e) 0.92, 90% interval 0.85 to 0.98.
Homologues: Orthologues: chimpanzee PZP (99% identical), macaque PZP (93% identical), rat Mug1l1 (58% identical), mouse Mug1 (57% identical), guinea pig Mug1 (57% identical), rat Cpamd8 (56% identical), mouse Gm7298 (56% identical), mouse Mug2 (55% identical), tropical clawed frog pzp (40% identical), tropical clawed frog a2ml1 (39% identical), zebrafish si:dkey-105h12.2 (37% identical), zebrafish a2ml (36% identical), and 16 more. Paralogues in human: A2M (72% identical), A2ML1 (37% identical), CPAMD8 (27% identical), CD109 (26% identical), C3 (23% identical), C4A (22% identical), C4B (22% identical), C5 (20% identical).
Diseases named in the same sentence as PZP in open-access papers:
PZP is named in the same sentence as 46 diseases in open-access papers, as found by Europe PMC text mining. Sharing a sentence is not in itself a finding about the gene and the disease. The quoted sentences say what the papers report.
hepatocellular carcinoma (7 papers, 2019 to 2025). A malignant tumor that arises from hepatocytes. "Recently, PZP has been reported to act as a potential biomarker for screening the risk of lung adenocarcinoma or prognosis of hepatocellular carcinoma in patients with type 2 diabetes." (PMID 36051914, 2022). "Located on chromosome 12 (12p13.31), the PZP expression level is positively correlated with macrophage and neutrophil levels to regulate the tumor immune microenvironment of hepatocellular carcinoma." (PMID 39851522, 2025). "In hepatocellular carcinoma, PZP has low expression in tumor tissues, and the downregulation of PZP is correlated with poor clinical outcomes." (PMID 33691685, 2021). "The gene encoding PZP is hypermethylated and expressed at low levels in hepatocellular carcinoma (HCC) tissue and cells, but the function of PZP in HCC cells remains unclear." (PMID 33471436, 2021). "The overall association scores for hepatocellular carcinoma were 0.210 for HOXD9, 0.174 for NDST3, 0.111 for PZP, 0.106 for E2F8, 0.061 for ADRA2B, and 0.029 for COL15A1." (PMID 31754347, 2019). "In hepatocellular carcinoma (HCC), silencing of tumor suppressor genes such as HHIP, MT1M, PZP, and TTC36 is a key driver of carcinogenesis." (PMID 41335282, 2025).
lung adenocarcinoma (4 papers, 2021 to 2022). A carcinoma that arises from the lung and is characterized by the presence of malignant glandular epithelial cells. "PZP has been identified as an unprecedented noninvasive indicator for screening lung adenocarcinoma in T2DM in our previous research." (PMID 34917649, 2021). "Besides, in our previous research, PZP was identified as a serum indicator for screening lung adenocarcinoma in T2DM." (PMID 34917649, 2021).
preeclampsia (4 papers, 2020 to 2025). Preeclampsia is a hypertensive disorder of pregnancy that is characterized by new-onset hypertension with proteinuria presenting after 20 weeks of gestation, and depending on mild or severe forms may initially present with severe headache, visual disturbances, and hyperreflexia. "Thus, functions of PZP or A2M family proteins other than protease inhibition might also be related to pregnancy-associated diseases such as preeclampsia." (PMID 32198464, 2020). "The upregulation of PZP represents a major maternal adaptation and the low placental expression of PZP is related to preeclampsia." (PMID 37762835, 2023). "Moreover, PZP is significantly downregulated in pathological conditions such as preeclampsia or HELLP syndrome." (PMID 40362347, 2025).
Hypertension (3 papers, 2023 to 2025). The presence of chronic increased pressure in the systemic arterial system. "The upregulated circulating proteins in PE+ (AMBP, VTN, CLU, F2, PZP, APCS, and HBB) are involved in blood pressure regulation, extracellular matrix dynamics, and immune system function, highlighting the pathogenesis of this hypertensive disorder in the context of inflammation and immune defense." (PMID 40673030, 2025).
Obesity (3 papers, 2021 to 2022). Accumulation of substantial excess body fat. "To verify this hypothesis, we constructed a PZP adipose tissue overexpression transgenic mouse model (PZP TG) and found that mice that specifically expressed PZP in adipose tissue were more resistant to HFD-induced obesity." (PMID 36051914, 2022). "To investigate whether the changes in PZP level also occurred in human obesity, we detected the serum levels of PZP in a cohort of individuals with a wide range of BMI and found that circulating PZP level inversely correlated with log2 (BMI)." (PMID 34514733, 2021). "Unlike ad libitum feeding, PZP KO mice showed a significant higher weight gain compared with WT mice when subjected to the IF regimen, thus PZP deficiency partially abolished the anti‐obesity effect of IF." (PMID 34514733, 2021). "Intermittent fasting (IF) (one day fasting-two days refeeding) for 12 weeks can activate BAT through pregnancy zone protein (PZP) secreted by the liver, so as to promote diet induced heat generation, and finally have the effect of anti-obesity." (PMID 36714578, 2022). "Considering that BAT is a critical thermogenic organ and activation of BAT contributes to increased energy expenditure and anti‐obesity effects, we next examined the response of BAT in PZP KO mice under IF and HFD condition." (PMID 34514733, 2021). "Taken together, the overexpression of PZP in adipose tissue helps anti-diet-induced obesity (DIO), and there are no necessary modifications of PZP by the liver for metabolic regulation." (PMID 36051914, 2022).
Alzheimer disease (2 papers, 2019 to 2023). A progressive, neurodegenerative disease characterized by loss of function and death of nerve cells in several areas of the brain leading to loss of cognitive function such as memory and language. "Pregnancy zone protein (PZP), as a suggested marker in Alzheimer’s disease, was also found to be differentially abundant." (PMID 37686821, 2023). "Pregnancy-independent expression of PZP is widely reported in diseases such as Alzheimer's disease, Parkinson's disease, rheumatoid arthritis, Behcet's syndrome, psoriasis, Chagas disease, viral infection, inflammatory bowel disease, and cancers." (PMID 31428227, 2019).
breast carcinoma (2 papers, 2021 to 2022). "Subsequent studies have reported that the expression of PZP in tumor tissues was lower than that in normal tissues, and the loss of PZP would promote the progression of breast cancer, laying the foundation for the potential of PZP protein in tumor therapy." (PMID 36051914, 2022).
bronchiectasis (2 papers, 2019 to 2025). Segmental, irreversible dilation of the bronchial tree resulting in the accumulation of secretions which leads to obstruction. "We speculate PZP may be involved in immunological tolerance in patients with bronchiectasis by interacting with NETs to modulate T-cell functions." (PMID 31264895, 2019). "Further mechanistic work is required to determine whether PZP is simply a marker of chronic neutrophilic inflammation or if it has a direct role in the pathogenesis of chronic infection in bronchiectasis." (PMID 31264895, 2019). "The identification of PZP in NETs in bronchiectasis is intriguing because it has no known antimicrobial effects." (PMID 31264895, 2019).
chronic kidney disease (2 papers, 2023 to 2024). Impairment of the renal function secondary to chronic kidney damage persisting for three or more months. "Moreover, our analyses support an increased risk of arterial stiffness post-PE, as indicated by abnormal PZP expression, an emerging biomarker for cardiovascular risk as identified in chronic kidney disease patients." (PMID 39587642, 2024).
colitis (2 papers, 2019 to 2025). Inflammation of the colon. "Of note, alpha-1-B glycoprotein (A1BG) was also decreased, whereas haptoglobin (HP), pregnancy zone protein (PZP), and hemopexin (HPX) were increased throughout the colitis progression in IL-10−/− mice." (PMID 30774653, 2019).
COVID-19 (2 papers, 2021 to 2022). A disease caused by infection with severe acute respiratory syndrome coronavirus 2. "Of the significantly dysregulated proteins, selected immune-related proteins PZP, SELENOP, PON1, and CBP2 were validated as candidate prognostic biomarkers for COVID-19 symptomatology." (PMID 34566994, 2021).
Miscarriage (2 papers, 2021 to 2025). A pregnancy that ends at a stage in which the fetus is incapable of surviving on its own, defined as the spontaneous loss of a fetus before the 22th week of pregnancy. "PZP has been regarded as a pregnancy-associated protein that is remarkably overexpressed in the decidua of recurrent and spontaneous miscarriage." (PMID 34917649, 2021).
osteoporosis (2 papers, 2019 to 2024). A condition of reduced bone mass, with decreased cortical thickness and a decrease in the number and size of the trabeculae of cancellous bone (but normal chemical composition), resulting in increased fracture incidence. "The genes identified in our study—LTBP1, PZP, ARID2, and HEBP1 in osteoporosis BRON patients—clearly support the previous evidence that angiogenesis, osteoclast activity, bone remodeling, and immune responses are critical underlying mechanisms." (PMID 31747953, 2019).
pregnancy disorder (2 papers, 2020 to 2023). A disorder that is related to pregnancy. "Altered expression of PZP was detected in early pregnancy disorders." (PMID 38069155, 2023).
viral infection (2 papers, 2019 to 2024). "Recent experiments using PZP knockout mice have shown that PZP also increases susceptibility to viral infection." (PMID 31264895, 2019).
abscesses (1 paper, 2022). "However, it was possible to observe that both the pZP and reZP groups were significantly more affected than the control group, which suggests that the pZP and reZP antigens increase the development of the abscesses at the injection sites." (PMID 35203165, 2022).
acute leukemia (1 paper, 2016). A clonal (malignant) hematopoietic disorder with an acute onset, affecting the bone marrow and the peripheral blood. "In addition to BRPF1/2/3, the PZP module is found in a range of proteins that also form translocation chimeras in acute leukemias, including JADE1/2/3 and AF10/17." (PMID 26626149, 2016).
acute pancreatitis (1 paper, 2019). An acute inflammatory process that leads to necrosis of the pancreatic parenchyma. "This mouse model has been previously used to understand the role of mouse PZP and MUG-1 proteins in acute pancreatitis, Trypanosoma cruzi infection, and drug pharmacokinetics." (PMID 30814992, 2019).
benign ovarian tumors (1 paper, 2021). "Previous research suggested that serum PZP levels are notably elevated in patients with ovarian cancer in comparison with those with benign ovarian tumors and in those with cervical or endometrial cancer in comparison with those with benign uterine myomas." (PMID 34917649, 2021).
dementia (1 paper, 2025). Loss of intellectual abilities interfering with an individual's social and occupational functions. "Specifically, the NCAM1 and PZP proteins showed sex-specific causal relationships with dementia in males and females, respectively." (PMID 40877285, 2025). "From sex-stratified Mendelian randomization using the SD-pQTLs, proteins NCAM1 and PZP showed significant causal relationship with dementia in males and females, respectively." (PMID 40877285, 2025).
fatty liver (1 paper, 2018). "To further determine which genes might play a significant role in the progression of fatty liver, we used real-time qPCR to detect the expression of 8 DEGs using clinical samples, including CD24, PZP, COL1A1, COL1A2, LUM, VCAN, THBS2 and EPHA3." (PMID 29769552, 2018).
glioma (1 paper, 2025). A benign or malignant brain and spinal cord tumor that arises from glial cells (astrocytes, oligodendrocytes, ependymal cells). "Additional roles in glioma have also emerged for proteins known to have an association with one sex compared to the other, including HCG, FSH, PZP, and ferritin." (PMID 40362575, 2025).
glomerulopathies (1 paper, 2023). "Particularly, PZP, IPSP, and IGHG1 also underlined the differences between particular glomerulopathies; the first two are of particular interest, as they distinguish FSGS and MN, unlike any other core protein." (PMID 37110557, 2023).
gout (1 paper, 2022). A condition characterized by painful swelling of the joints, which is caused by deposition of urate crystals. "Besides, PZP in SF-derived exosomes of RA was higher than other groups, while PZP in axSpA and OA was higher than gout, and PZP in axSpA was higher than OA." (PMID 35359923, 2022).
Insulin resistance (1 paper, 2023). Increased resistance towards insulin, that is, diminished effectiveness of insulin in reducing blood glucose levels. "Besides recapturing known biomarkers for insulin resistance, we have been able to discover three novel proteins, to the best of our knowledge, associated with insulin resistance: IGHD, IGKC and PZP." (PMID 37903988, 2023).
liver cancer (1 paper, 2023). An epithelial or non-epithelial malignant neoplasm that arises from the liver. "These analyses demonstrated that HHIP was a key TSG controlling liver cancer cell proliferation and cell viability; in fact, only modest changes in cell viability were achieved when individually targeting MT1M, PZP, and TTC36." (PMID 37120619, 2023).
lung carcinoma (1 paper, 2021). "The results showed that PZP mRNA was downregulated in lung cancer tissues and significantly correlated with immune cell infiltration." (PMID 33691685, 2021). "Besides, we also analyzed the expression of PZP and its correlations with immune cell infiltration in lung cancer." (PMID 33691685, 2021).
parasitemia (1 paper, 2019). "This is in agreement with previous observations demonstrating that PZP and MUG-1 deficient mice had significantly lower parasitemia than WT mice after infection with T. cruzi." (PMID 30814992, 2019).
tumor (12 papers, 2015 to 2025). "We identified 10 methylation-driven genes, of which PZP was significantly hypermethylated and poorly expressed in tumor tissue." (PMID 33471436, 2021). "In the mRNA group, ZIC5, C12orf75, C1QL1, TMEM74, and GNAZ were significantly upregulated in tumor tissues compared to the adjacent control; PZP and FAM65C were significantly downregulated compared to the adjacent control." (PMID 31156698, 2019). "Tumor PZP had a 12.5 kb inverted insertion originating from chromosome 6 containing ENPP1 exons 19 to 25 including the stop codon." (PMID 25762628, 2015). "PZP was found as an anti-tumor gene with aberrant DNA methylation in many cancers." (PMID 38374122, 2024). "PZP might be able to promote tumor regression through interaction with these ligands." (PMID 35945555, 2022). "Therefore, serum PZP may be derived from tumor-related immune cells, but further studies still need to confirm the source of PZP and its diagnostic value by large-scale analysis." (PMID 33691685, 2021). "Next, we systematically explored the relationship between the expression of 37 common DEGs in tumor tissues and OS rate in TCGA and constructed a novel prognosis-related model composed of five genes (AURKA, PZP, RACGAP1, ACOT12 and LCAT)." (PMID 34336648, 2021). "Next, we systematically explored the relationship between the expression of 37 common DEGs in tumor tissues and overall survival (OS) rate of HCC patients in TCGA and constructed a novel prognostic model composed of five genes (AURKA, PZP, RACGAP1, ACOT12 and LCAT)." (PMID 34336648, 2021).
cancer (8 papers, 2017 to 2024). A tumor composed of atypical neoplastic, often pleomorphic cells that invade other tissues. "The stop-gain mutation (rs117889746) of the PZP gene in the BRONJ cancer group was significantly identified in the additive trend model analysis." (PMID 31747953, 2019). "The statistical technique using the traditional genetic model showed that the stop-gain mutation (rs117889746) in exon 15 of the PZP gene was significantly associated with the occurrence of BRONJ in 2 of the 13 cancer patients (1 homozygous and 1 heterozygous)." (PMID 31747953, 2019). "PZP is a protein belonging to the α-2-microglobulin superfamily, which is involved in inflammatory responses and immune cell activation in cancer." (PMID 38542389, 2024). "Previous research has also uncovered the role of PZP in cancers." (PMID 33691685, 2021). "Thus, whether PZP is a pan-cancer or pan-adenocarcinoma biomarker in T2DM needs to be further explored." (PMID 34917649, 2021).
bacterial infection (1 paper, 2020). "Therefore, it might be possible that PZP and A2ML1 play a different role in some regulatory mechanism for inflammation and bacterial infection between human and marmoset species." (PMID 32198464, 2020).
PZP also shares sentences with these, for which no sentence is quoted: infection (3 papers); diabetes (2); type 2 diabetes (2); abortion (1); adenocarcinoma (1); asthma (1); endometrial cancer (1); Fever (1); Graves disease (1); HELLP syndrome (1); hip fracture (1); immune disorders (1); inflammatory bowel disease (1); metabolic disorder (1); ovarian carcinoma (1).